MOG (myelin oligodendrocyte glycoprotein)
Diseases named in the same sentence as MOG in open-access papers (continued):
Sharing a sentence is not in itself a finding about the gene and the disease.
demyelinating disease (continued). "Myelin oligodendrocyte glycoprotein (MOG) antibody-associated disease (MOGAD) and autoimmune glial fibrillary acidic protein (GFAP) astrocytopathy are demyelinating diseases of the central nervous system (CNS) that have received increasing attention in recent years." (PMID 41333477, 2025). "MOG, located 100 kb telomeric to human leukocyte antigen (HLA) class I (HLA F), is highly immunogenic and has been suspected to be an important target of demyelinating diseases such as MS." (PMID 40332104, 2025). "The detection of cerebrospinal fluid and serum of autoimmune encephalitis and demyelinating diseases of the CNS, including MOG-IgG and mGluR5-IgG, should be strengthened in order to make a precise diagnosis and develop a comprehensive treatment plan in a timely manner." (PMID 39151524, 2024). "C1q may activate myelin by binding to myelin oligodendrocyte glycoprotein, potentially playing a role in demyelinating diseases." (PMID 39416682, 2024). "Myelin oligodendrocyte glycoprotein (MOG) is a minor transmembrane glycoprotein located in the outermost membranes of the myelin sheath that has long been an important target molecule for animal models of demyelinating diseases." (PMID 38333186, 2023). "Currently, no data on the prevalence of PHOMS in other demyelinating diseases including aquaporine-4-IgG-positive neuromyelitis optica spectrum disease (AQP4 + NMOSD) or myelin oligodendrocyte glycoprotein-IgG-associated disease (MOGAD) are reported." (PMID 36245037, 2023). "It is therefore possible that the ratio of NfL-to-MOG Abs could have a prognostic significance indicating that patient with high NfL-to-MOG Abs ratio may have a monophasic demyelinating disease or MOGNR." (PMID 36993944, 2023). "Based on these observations, it has been speculated that MOG is a candidate autoantigen in human demyelinating disorders." (PMID 36816137, 2023). "In this study we have shown that mice with HSV-IL-2-induced and MOG-induced demyelinating diseases demonstrated a similar pattern and distribution of demyelination in their brain, spinal cord, and optic nerves, while no demyelination was detected in the optic nerves of MBP- and PLP-injected mice." (PMID 36817487, 2023). "In conclusion, measuring both NfL and MOG Abs levels in patients at onset of demyelinating disease could be used to follow the different courses of MOGAD." (PMID 36993944, 2023). "The presence of MOG antibodies in ADEM was higher than that in other demyelinating disorders." (PMID 36352355, 2022). "For example, anti-NMDAR encephalitis may co-exist with a demyelinating disease in the presence of anti-MOG or anti-GFAP antibodies." (PMID 36211351, 2022). "For patients with demyelinating disease, as indicated by imaging results, CSF should be examined for anti-aquaporin-4 antibody, anti-myelin oligodendrocyte glycoprotein antibody, anti-myelin basic protein antibody, and oligoclonal bands to further clarify the diagnosis." (PMID 36523348, 2022). "Since MOG antibody-related demyelination disease presents with typical clinical characteristics and has treatment outcomes distinct from other IIDDs, it is now considered an independent disease called MOG-EM." (PMID 34093424, 2021). "Second, although the results of patients with MOG antibody-associated demyelinating diseases were consistent with those of EAE mice, it is still inconclusive whether the EAE model perfectly simulates MOG antibody-associated demyelinating diseases." (PMID 34039371, 2021). "We describe four pediatric cases presenting clinically with ON, with different etiopathogenetic pictures: one case had a probable infective etiology, while the others were associated with different demyelinating disorders (MS, NMO, syndrome related to MOG-IgG)." (PMID 34682120, 2021).
demyelinating disease (continued). "Assuming a newly acquired demyelinating disorder with optic nerve involvement and afferent gait disturbance, we tested for MOG-IgG and Aquaporin 4 (AQP4) antibodies in serum and CSF, being both relevant mediators in autoimmune demyelinating syndromes of the CNS." (PMID 34266413, 2021). "Inflammatory responses against MBP, MOG and MAG are known to cause demyelinating diseases." (PMID 32000863, 2020). "The high specificity of both AQP4 and MOG antibody assays means that in clinical practice, where there is a characteristic clinical presentation, a positive antibody result can be taken as being indicative of NMOSD or MOG antibody-related demyelinating disease respectively." (PMID 31636597, 2019). "MOG is a myelin protein expressed exclusively on the surface of myelin sheaths and membranes of oligodendrocytes and a potential target molecule for the autoimmune response in demyelinating diseases." (PMID 31870389, 2019). "In addition, the distribution of the spinal cord lesions is subtly different with lesions of the high cervical spine (C1/2) being seen in NMOSD and lesions extending all the way to the conus being seen in MOG antibody-related demyelinating disease." (PMID 31636597, 2019). "Mayer and colleagues performed epitope recognition studies of MOG Abs from several demyelinating diseases and seven distinct binding patterns were found." (PMID 28533781, 2017). "Therefore, it is necessary to also study MOG autoreactivity in the marmoset (Callithrix jacchus), in which MOG-induced EAE resembles human demyelinating diseases more closely." (PMID 28533781, 2017). "Thus, IgG antibodies specific for native MOG, indicative for central nervous system (CNS) demyelinating diseases in children, are transiently increased in a subgroup of patients with IM." (PMID 26907324, 2016). "Thus, MOG-AD constitutes an important differential diagnosis in suspected demyelinating disease." (PMID 36472724, 2024). "In Indonesia, it is often challenging to ascertain the exact type of the demyelinating disease, because of the inability to perform a complete diagnostic workup, especially regarding the limited facilities for testing aquaporin 4 antibodies (AQP4-IgG) or anti-MOG antibodies." (PMID 34327021, 2021). "In previous Mayo clinic reports, Lennon and her colleagues identified patients with GFAP astrocytopathy with several additional kinds of autoantibody, including NMDAR antibody, AQP4 antibody, and MOG antibody, which suggests an immune encephalitis or demyelinating disorder." (PMID 29755396, 2018). "However, evidence of anti-MOG antibody pathogenicity in demyelinating disorders is still limited." (PMID 27577085, 2016). "When suspecting demyelinating disease, practitioners should order serum testing for anti-AQP4 and anti-MOG." (PMID 39741598, 2024). "To assess the frequency of MOG-IgA seropositivity, we investigated MOG-IgA, MOG-IgG, and MOG-IgM in 1339 patients with CNS demyelination (MS, n = 865; NMOSD, n = 196; other demyelinating diseases, n = 278)." (PMID 37548987, 2023). "In this longitudinal study, a subgroup of patients with demyelinating disorders was double-seronegative for aquaporin 4 (AQP4) IgG and MOG-IgG but seropositive for MOG-IgA." (PMID 37548987, 2023). "MOG-IgA was positive in 3 of 50 patients (6%) with NMOSD, in 5 of 228 patients (2%) with other demyelinating diseases, and in 10 of 848 patients (1%) with MS who were double-seronegative for AQP4-/MOG-IgG." (PMID 37548987, 2023). "This is not only true for clinical research: MOG-induced animal models, such as experimental autoimmune encephalomyelitis (EAE), have been widely used as models of demyelinating diseases in general and MS in particular." (PMID 38333186, 2023). "Myelin oligodendrocyte glycoprotein (MOG) antibody, expressed in the outermost layer of the myelin sheaths in the mammalian central nervous system (CNS), mediates a variety of demyelinating diseases." (PMID 36352355, 2022).
demyelinating disease (continued). "MOG-IgG-related disease is now considered as a disease entity in its own right, immunopathogenetically distinct from MS and from AQP4-IgG-related demyelinating diseases." (PMID 33281728, 2020). "The results of this study have further confirmed that MOG-IgG-related neuroinflammation is immunopathogenetically distinct from classical MS and AQP4-IgG-induced demyelinating disorders." (PMID 33281728, 2020). "The localization of MOG at the external lamellae of myelin sheaths and on the surface of oligodendrocytes membrane is not the only hint suggesting this protein may be involved in the interaction with the immune system and pathophysiology of demyelinating disorders." (PMID 33374173, 2020). "Significant information about MOG in the CNS immune response came from experimental autoimmune encephalomyelitis (EAE), an important animal model in demyelinating diseases investigation." (PMID 30765742, 2019). "In order to investigate how PTP gene expression changes during a time course of disease, we quantified PTP mRNA expression in CNS samples of C57/Bl6 mice undergoing a MOG-induced EAE, a well adopted model of demyelinating disease." (PMID 22792334, 2012). "In contrast to MOG-EAE, CXCR3 appears to promote the lymphocyte accumulation inside the CNS in some virus-induced demyelinating disease models." (PMID 22233170, 2012). "In demyelinating diseases of the central nervous system, aquaporin 4 (AQP4) and myelin oligodendrocyte glycoprotein (MOG) have emerged as interesting antibody targets." (PMID 23035757, 2012). "Thus, the detection of high-titer MOG-IgG might not only serve as a valuable biomarker in AQP4-IgG negative NMO and HR-NMO patients, but possibly play a role as pathogenic factor in human demyelinating diseases, although this needs to be further investigated." (PMID 22204662, 2011). "Several investigations using cell-based assays with mammalian cells expressing the complete human MOG protein have emphasized the presence of MOG-IgG in patients with non-MS demyelinating disorders of the CNS." (PMID 40362691, 2025). "Acute transverse myelitis and other demyelinating disorders were ruled out by the negative serology (MOG IgG, NMO IgG), acellular CSF, and the highly specific anterior cord-only signal abnormality on MRI, which is unlike typical inflammatory lesions." (PMID 41523461, 2025). "Serological and CSF immunological testing for Myelin Oligodendrocyte Glycoprotein (MOG)-IgG and Neuromyelitis Optica (NMO)-IgG, performed to definitively exclude specific demyelinating disorders such as MOG antibody disease (MOGAD) and NMO Spectrum Disorder (NMOSD), was negative." (PMID 41523461, 2025). "The results of autoantibodies against AE and demyelinating diseases in CSF and serum showed that anti-MOG abs were negative in CSF and serum (1:10), CSF and serum anti-NMDAR abs were (1:1) and (1:10), respectively." (PMID 38664672, 2024). "In addition, the report showed that autoantibodies against AE and demyelinating diseases were positive in CSF and serum, the anti-NMDAR abs titers were (1:10) and (1:10) in CSF and serum, MOG-ab in CSF and serum were (1:3.2) and (1:32), respectively." (PMID 38664672, 2024). "Although the appearance of MOG antibodies is relatively rare in post-COVID-19-vaccine demyelinating diseases, MOGAD should be considered in patients with central nervous system (CNS) demyelinating diseases after receiving a SARS-CoV-2 vaccine." (PMID 35299613, 2022). "Of the 14 patients that were diagnosed with demyelinating disease (DD), 2 had relapsing-remitting MS, 1 had a clinically isolated syndrome, 3 had tumefactive MS, 3 were classified as untyped or neurodegenerative MS, 4 had ADEM, and 1 had anti-MOG syndrome." (PMID 34100959, 2021). "MOG-abs have been mentioned in the literature for almost 30 years, although their role in demyelinating diseases has not been fully elucidated until this decade." (PMID 33584514, 2020).
demyelinating disease (continued). "At last follow-up, ten were diagnosed as MS, five as ADEM, six as CIS (three ON, two TM, one hemiplegia), two as NMOSD, and four as non-MS relapsing demyelinating diseases with anti-MOG-Abs all named (ADS MOG+)." (PMID 31785610, 2019). "Finally, specific antibodies (AQP4/MOG/MBP) did not detect any signs of demyelinating diseases in the central nervous system (CNS)." (PMID 34791569, 2022). "Pathophysiology might probably be different in patients with a known MOG positive demyelinating disease and a later occurring NMDAR encephalitis compared to patients with NMDAR encephalitis who later suffer a demyelinating relapse triggered by MOG IgG." (PMID 36384491, 2022). "In a next step, we analyzed whether the individual MOG isoforms are useful for discriminating a non-MS demyelinating disease from MS or HC." (PMID 34131067, 2021). "This could explain why some MOG-Ab positive patients received a final diagnosis of “other demyelinating disorders” defined by the evidence of an inflammatory disorder not fulfilling diagnostic criteria for MS, NMOSD, or ADEM." (PMID 29063242, 2017). "Furthermore, myelin oligodendrocyte glycoprotein (MOG) antibody was not available in our department, which was reliably associated with a spectrum of demyelinating disorders including relapsing paediatric demyelination." (PMID 27725883, 2016). "Furthermore, the percentage of patients with different clinical presentations of a non-MS demyelinating disease (cerebral, opticospinal, or mixed presentation) or monophasic or recurrent course at the last follow-up was comparable in all 3 MOG isoform binding patterns." (PMID 34131067, 2021). "In addition, MOG T cell-receptor and B cell-receptor do spontaneously developed NMO-like optic nerve and spinal cord lesions suggesting that MOG-specific immune responses might initiate demyelinating diseases in the CNS." (PMID 26920678, 2016). "B cell depletion with anti-CD20 before full-length MOG-induced, but not ECD-induced, demyelinating disease restored T cell reactivity toward the immunodominant epitope of MOG35–55, suggesting the B cell–mediated control of encephalitogenic epitopes." (PMID 39330967, 2024). "Patients with non-MS demyelinating diseases included s/p CIS (n = 17), s/p MOG+ (n = 3), s/p ADEM (n = 1), as well as patients with RIS (n = 3)." (PMID 35450065, 2022). "Thus, while the cervical cord showed significant downregulation of CNPase and MOG only but not MBP, the thoracic region of the spinal cord showed significant downregulation of all three myelin proteins at the peak of demyelinating disease." (PMID 39292341, 2025).
encephalitis (171 papers, 2009 to 2026). An acute inflammatory process affecting the brain parenchyma. "The co-occurrence of anti-N-methyl-D-aspartate receptor (NMDAR) encephalitis and myelin oligodendrocyte glycoprotein (MOG) antibody-associated disease in a single patient is rare." (PMID 42253986, 2026). "Both cortical and subcortical abnormalities in DWM are more frequently associated with anti-MOG encephalitis." (PMID 40648981, 2025). "In recent years, the number of case reports concerning fluid-attenuated inversion recovery (FLAIR) hyperintense cortical lesions in myelin oligodendrocyte glycoprotein (MOG) -associated encephalitis with seizures (FLAMES) has been gradually increasing." (PMID 40740785, 2025). "Severe MOGAD often presents with bilateral ON, MOG-associated encephalitis, cortical encephalitis with seizures, and longitudinally extensive transverse myelitis (LETM) resulting in persistent motor deficits." (PMID 40943458, 2025). "In 8 out of 33 (24%) pediatric cases of MOG-antibody-associated encephalitis, initial MRI scans of the brain were normal." (PMID 40078175, 2025). "Other immune mediated CNS diseases demonstrating lateralisation are Rasmussen’s encephalitis as well as unilateral cortical FLAMES (FLAIR-hyperintense Lesions in Anti-MOG-associated Encephalitis with Seizures)." (PMID 40529356, 2025). "During the patient’s fifth attack, the patient experienced seizures again, and FLAIR showed new lesions on the right frontal cortical area, which were termed as FLAIR-hyperintense lesions in anti-MOG-associated encephalitis with seizures (FLAMES)." (PMID 39981240, 2025). "In this study, the median age of the children was 9 years, consistent with a recent study, suggesting an age-dependent nature of MOG-Ab-associated encephalitis." (PMID 40740785, 2025). "Mycoplasma pneumoniae (M. pneumoniae) infections can cause oligodendrocyte glycoprotein (MOG) antibody-associated encephalitis." (PMID 39334394, 2024). "The patient was diagnosed with overlapping syndrome of anti-MOG antibody-associated disease and anti-mGluR5 encephalitis mainly based on the clinical symptoms and further test of the antibody in serum." (PMID 39151524, 2024). "Pontine brain lesions-abnormal signals in the bilateral pontine brachium have a complex etiology, and MOG antibody encephalitis has gradually been recognized as one of the causes, but the diagnosis is easy to miss." (PMID 39121314, 2024). "A similar contradiction was observed between independent research groups in an identical model of myelin oligodendrocyte glycoprotein (MOG) antibody-associated encephalomyelitis/encephalitis." (PMID 38673843, 2024). "Over the past few years, anti-NMDAR encephalitis has been reported to be associated with MOG antibodies." (PMID 38895128, 2024). "Encephalitis is the most frequent central nervous system manifestation of M. pneumoniae infections in children, but MOG-IgG-associated encephalitis induced by M. pneumoniae infections has been rarely reported previously." (PMID 39334394, 2024). "This MOGAD subtype is named FLAMES (FLAIR hyperintense cortical lesions in MOG-associated encephalitis with seizures)." (PMID 39062226, 2024). "Three children with MOG-IgG-associated encephalitis due to M. pneumoniae infections who were treated at our hospital from September to November 2023 were included in the study." (PMID 39334394, 2024). "A diagnosis of FLAIR-hyperintense lesions in anti-MOG-associated encephalitis with seizures (FLAMES) was made, and the patient was treated with intravenous methylprednisolone for five days, leading to clinical remission within days." (PMID 39479094, 2024). "This led to a diagnosis of overlapping syndrome involving MOG antibody-associated encephalitis and mGluR5 antibody autoimmune encephalitis." (PMID 39151524, 2024). "Sometimes, anti-NMDAR encephalitis is accompanied by other immune diseases, such as progressive systemic sclerosis and myelin oligodendrocyte glycoprotein antibody-associated encephalitis." (PMID 38145121, 2023).